HAX1 (HCLS1 associated protein X-1)
Diseases named in the same sentence as HAX1 in open-access papers (continued):
Sharing a sentence is not in itself a finding about the gene and the disease.
lymph node metastasis (4 papers, 2013 to 2016). "High HAX-1 expression was associated with lymph node metastasis (P < 0.01), M classification (P < 0.01), and clinical stage (P < 0.01)." (PMID 26871467, 2016). "Overexpressed HAX-1 is associated with lymph node metastasis, distant metastasis, and clinical stage (all P < 0.05)." (PMID 26871467, 2016). "The expression level of HAX-1 mRNA was positively correlated with lymph node metastasis, and was a risk factor of lymph node metastasis in the patients with ESCC (Wald χ2 = 12.743, P = 0.000)." (PMID 23531395, 2013). "HAX-1 mRNA expression level was a risk factor of lymph node metastasis in patients with ESCC (P = 0.000)." (PMID 23531395, 2013). "The present study demonstrated that the expression of HAX-1 was significantly associated with lymph node metastasis, muscular layer invasion and clinical stage in CRC, which suggested that HAX-1 may be important in the progression and metastasis of CRC." (PMID 26062578, 2015). "Previous reports have demonstrated that patients with esophageal squamous cell carcinoma overexpressing HAX-1 are more likely to exhibit lymph node metastasis and have a poor prognosis." (PMID 26062578, 2015). "The level of HAX-1 mRNA (Wald χ2 = 55.641, P = 0.000) and protein (Wald χ2 = 0.7.929, P = 0.005) were risk factors of survival, but lymph node metastasis (Wald χ2 = 0.506, P = 0.477) was not a risk factor of survival in the patients with ESCC." (PMID 23531395, 2013). "The level of HAX-1 mRNA (P = 0.000) and protein (P = 0.005) were risk factors of survival, but lymph node metastasis (P = 0.477) was not." (PMID 23531395, 2013). "We observed that HAX-1 expression is elevated in NPC and is correlated with lymph node metastasis, M classification, clinical stage, and poor prognosis." (PMID 26871467, 2016).
periodontal disease (4 papers, 2019 to 2025). "They observed that patients with pathogenic variants in ELANE present with more severe periodontal disease than patients with HAX1 or unknown genetic defects." (PMID 32625202, 2020).
laryngeal carcinoma (3 papers, 2016 to 2025). Carcinoma that arises from the laryngeal epithelium. "It is proved that miR-125a/HAX-1 axis to be associated with chemosensitivity in laryngeal cancer stem cells." (PMID 27880721, 2016). "These dates strongly suggested the promotion of microRNA-125a/HAX-1 axis on chemotherapy of laryngeal carcinoma." (PMID 27880721, 2016). "We demonstrate that miR-125a-dependent inhibition of HAX-1 re-sensitizes laryngeal cancer stem cells to cisplatin through mitochondrial apoptosis pathway." (PMID 27880721, 2016).
metastatic tumors (3 papers, 2010 to 2024). "Importantly, we found that human (colon to liver) metastatic tumors exhibited higher protein levels of EIF3H and HAX1 when compared with the paired primary tumor tissue and adjacent normal tissue from human patients with CRC." (PMID 38514606, 2024).
nasopharyngeal carcinoma (3 papers, 2016 to 2024). A carcinoma arising from the nasopharyngeal epithelium. "We examined the expression of HAX-1 in nasopharyngeal carcinoma (NPC) and experimentally manipulated its expression." (PMID 26871467, 2016). "We used immunohistochemical analysis to detect the expression of HAX-1 in nasopharyngeal carcinoma (NPC) and non-cancerous nasopharyngeal tissues." (PMID 26871467, 2016).
prostate carcinoma (3 papers, 2021 to 2025). A carcinoma that arises from epithelial cells of the prostate gland. "Another research revealed that HAX-1 suppresses the programmed cell death of prostate carcinoma cells via inhibiting the activation of caspase-9." (PMID 35602302, 2022). "HAX1 also represses apoptosis in prostate cancer through inhibiting caspase‐9 activation." (PMID 34755451, 2021).
Shwachman-Diamond syndrome (3 papers, 2011 to 2024). "Among them, 26 have chronic granulomatous disease (48.1% of all phagocytic diseases), 8 have Shwachman-Diamond syndromes (14.8%), 6 have HAX1 deficiencies (11.1%), 2 have Glycogen storage diseases type 1b (3.7%), and 2 have Elastase deficiency (3.7%)." (PMID 37559153, 2023). "Neutrophil elastase defects, HAX1 def., X-linked neutropenia (WAS), Shwachman-Diamond syndrome, etc." (PMID 38720948, 2024).
colorectal tumor (2 papers, 2015 to 2016). "To compare expression levels of KDM4B and HAX1 in colorectal tissues, we performed quantitative RT- PCR and western blot analysis to examine the expression of HAX1 in the 24 primary colorectal tumor samples and 24 adjacent normal colorectal normal tissues." (PMID 27506941, 2016). "The present study aimed to analyze the potential prognostic significance of HAX-1 in CRC by detecting its expression levels in human colorectal tumor tissues, and to assess the role of HAX-1 in apoptosis and proliferation using gene-overexpression and silencing methods." (PMID 26062578, 2015).
glioma (2 papers, 2021 to 2022). A benign or malignant brain and spinal cord tumor that arises from glial cells (astrocytes, oligodendrocytes, ependymal cells). "HCLS1‐associated protein X‐1 (HAX1), an anti‐apoptotic molecular, overexpresses in glioma." (PMID 34755451, 2021). "Decreased expression of phosphorylated Drp caused by HAX1 was found in glioma cells." (PMID 34755451, 2021). "HAX1 knockdown could cause a decrease of proliferation, migration and invasion of glioma cells cultured in hypoxia." (PMID 34755451, 2021). "Silencing of HAX1 could cause an increased apoptosis of glioma cells cultured in hypoxia." (PMID 34755451, 2021). "Our results demonstrated that higher expression of HAX1 was found in glioma cells survived in hypoxia." (PMID 34755451, 2021). "Western blotting, qRT‐PCR, Transwell assay, TUNEL assay, wounding healing assay, clone formation, tumour xenograft model and immunohistochemical staining were used to investigate the role of HAX1 in glioma." (PMID 34755451, 2021). "In conclusion, our study suggested that HAX1 promoted survival of glioma cells in hypoxic environment via AKT/Drp signal pathway." (PMID 34755451, 2021). "Silencing of HAX1 also decreased the proliferation, migration and invasion of glioma cells cultured in hypoxia." (PMID 34755451, 2021). "In conclusion, our study demonstrated that HAX1 played an important role in glioma cells in hypoxia." (PMID 34755451, 2021). "To further determine the role of HAX1 in glioma cell cultured in hypoxia, we designed small interference RNA (si‐RNA) to silence the expression of HAX1." (PMID 34755451, 2021). "Deng X, Guo XB and their colleague have demonstrated that HAX1 regulates glioma tumour through impacting glioma cells and endothelial progenitor cells." (PMID 34755451, 2021). "HAX1 knockdown significantly reduced tumour volume of glioma tumour." (PMID 34755451, 2021). "HAX1 also increased apoptosis of glioma cells cultured in hypoxia." (PMID 34755451, 2021). "HAX1 knockdown also promoted the apoptosis of glioma cells in hypoxia." (PMID 34755451, 2021). "Increased mitochondrial fission could prevent glioma cells from the damage induced by HAX1 knockdown in hypoxia." (PMID 34755451, 2021). "HIF‐1α was discovered to improve the expression of HAX1 in glioma cells cultured in hypoxia." (PMID 34755451, 2021). "In this study, we found that HAX1 was upregulated in glioma cell cultured in hypoxia." (PMID 34755451, 2021). "HAX1 regulated by HIF‐1α was increased in glioma cells cultured in hypoxia." (PMID 34755451, 2021). "And then, we used p‐AKT agonist SC‐79 (5 μg/ml for 1 h) to treat glioma cells after HAX1 knockdown." (PMID 34755451, 2021). "The growth of glioma tumour was slower after HAX1 knockdown." (PMID 34755451, 2021). "Importantly, recent studies reported that HAX1 was overexpressed in glioma and inhibits apoptosis of glioma." (PMID 34755451, 2021). "The effect of si‐HAX1 on glioma cell was confirmed by qRT‐PCR and Western blotting." (PMID 34755451, 2021). "This study provides a new understanding of the mechanism of HAX1 in glioma." (PMID 34755451, 2021). "Silencing of HAX1 was also able to induce mitochondrial fission due to the damage of mitochondrial function, while induction of mitochondrial fission could restrain the effect of HAX1 knockdown on glioma cell cultured in hypoxia." (PMID 34755451, 2021). "Our study focuses on the effect of HAX1 on glioma in hypoxic environment." (PMID 34755451, 2021). "Furthermore, HAX1 was found to regulate glioma cells through phosphorylated AKT/Drp signal pathway." (PMID 34755451, 2021). "HIF‐1α could increase the expression of HAX1 to protect glioma cell in hypoxia." (PMID 34755451, 2021). "Inhibition of mitochondrial fission could reduce the effect of HAX1 in glioma cells." (PMID 34755451, 2021). "Therefore, we speculated that HAX1 served as downstream of HIF‐1α to regulate glioma cell in hypoxia." (PMID 34755451, 2021).
glioma (continued). "However, the role of HAX1 in glioma cell surviving in hypoxic environment remains unclear." (PMID 34755451, 2021). "However, the role of HAX1 in glioma cell cultured in hypoxia remains unclear." (PMID 34755451, 2021). "Therefore, we first tested whether HIF‐1α regulated the expression of HAX1 in glioma." (PMID 34755451, 2021). "To further investigate whether HAX1 serves as a downstream of HIF‐1α to maintain the survival ability and characteristics of glioma, we established LV3‐pGLV‐H1 + Puro plasmids with pcDNA‐HAX1 or control oligonucleotides (Lenti‐HAX1 and Lenti‐NC) to overexpress HAX1 protein expression." (PMID 34755451, 2021). "To further investigate whether HAX1 enhances the mitochondrial fission by AKT/Drp signal pathway, we detected the protein level of p‐AKT after HAX1 knockdown and found that HAX1 knockdown reduced the level of p‐AKT in glioma cells." (PMID 34755451, 2021).
hepatoma (2 papers, 2022 to 2025). "HCLS1-associated protein X-1 (HAX-1) was observed to be significantly upregulated in human hepatoma tissues and demonstrated its ability to enhance cell proliferation." (PMID 40357287, 2025).
myelodysplastic syndrome (2 papers, 2018 to 2022). A clonal hematopoietic disorder characterized by dysplasia and ineffective hematopoiesis in one or more of the hematopoietic cell lines. "Mutations in the HAX1 gene can cause an autosomal recessive form of SCN-characterized low blood neutrophil count from birth, increased susceptibility to recurrent and life-threatening infections, and preleukemia predisposition." (PMID 30598852, 2018).
neuroblastoma (2 papers, 2012 to 2022). Neuroblastoma (NB) is the most common solid, extracranial childhood tumor. "Considering that HAX-1 plays important role in neurons apoptosis, HAX-1-mediated anti-apoptosis was evaluated not only in MCF-7 cells, but also in neuroblastoma SH-SY5Y cells." (PMID 35379774, 2022).
ovarian carcinoma (2 papers, 2013 to 2014). A malignant neoplasm originating from the surface ovarian epithelium. "Together, these data establish a dominant role for Hax-1 in LPA stimulated invasive migration of ovarian cancer cells." (PMID 25053987, 2014). "Results from such an analysis clearly indicated that the expression of Hax-1 was increased in ovarian cancer cell lines compared to HOSE cells." (PMID 25053987, 2014). "The elevated levels of expression of Hax-1 seen in ovarian cancer cells along with its previously established role on cell migration prompted us to investigate the role of Hax-1 in LPA or FBS stimulated migration of ovarian cancer cells." (PMID 25053987, 2014). "We demonstrate here that the expression of Hax-1 is highly elevated in a panel of ovarian cancer cells and the silencing of Hax-1 inhibited basal as well as serum- or LPA-stimulated migration by more than 50%." (PMID 25053987, 2014). "Similar to the results obtained from the wound-healing assay, LPA- as well as FBS-stimulated invasive migration of ovarian cancer cells was significantly attenuated by the silencing of Hax-1." (PMID 25053987, 2014). "In summary, our results conclusively establish for the first time that Hax-1 is critically required for the Rac1-cortactin interaction and subsequent invasive migration of ovarian cancer cells." (PMID 25053987, 2014). "In testing this hypothesis, we report here that Hax-1 shows an increased expression in ovarian cancer cells and silencing of Hax-1 critically impairs the migration of the representative SKOV3 cells in response to LPA." (PMID 25053987, 2014). "Results focused on resolving the role of Hax-1 in ovarian cancer pathophysiology indicate that Hax-1 is overexpressed in ovarian cancer cells and the silencing of Hax-1 inhibits lysophosphatidic acid (LPA)- or fetal bovine serum-stimulated migration of these cells." (PMID 25053987, 2014). "Thus our results presented here describe for the first time that Hax-1 interaction is required for the association between Rac1 and cortactin and that these multiple interactions are required for the LPA-stimulated migration of SKOV3 ovarian cancer cells." (PMID 25053987, 2014). "Therefore, we first sought to investigate whether the expression of Hax-1 is increased in ovarian cancer cells in which Gα13-signaling plays a major role in invasive cell migration." (PMID 25053987, 2014). "In light of the findings that LPA plays a dominant role in ovarian cancer cell migration, the observation that LPA-stimulated migration requires Hax-1 is quite significant." (PMID 25053987, 2014). "Lysates from a panel of ovarian cancer cells including SKOV3, HeyA8, OVCAR3, 2008, OVCA429 cells and control human ovarian surface epithelial cells (HOSE) were subjected to immunoblot analysis using antibodies specific to Hax-1." (PMID 25053987, 2014). "Thus, the results presented here define a critical scaffolding role for Hax-1 in LPA-stimulated Rac1-cortactin interaction and subsequent ovarian cancer cell migration." (PMID 25053987, 2014). "Our results also indicate that the competitive inhibition of the interaction between endogenous Hax-1 and Rac1 or Hax-1 and cortactin by the ectopic expression of any of these domains led to a decrease in LPA-stimulated migration of ovarian cancer cell line SKOV3." (PMID 25053987, 2014).
periodontitis (2 papers, 2019 to 2025). An acute or chronic inflammatory process that affects the tissues that surround and support the teeth. "Cisplatin was reported to be an HAX1 inhibitor, thus an understanding of its effects on gingival epithelial tissues may be useful to elucidate the etiology of anticancer drug-induced periodontitis." (PMID 40881345, 2025).
viral infection (2 papers, 2018 to 2023). "Since HAX1 exhibits significant anti-CCHFV activity in vitro, we then asked whether HAX1 also has an impact on virus infection in vivo." (PMID 37963884, 2023). "Since the mitochondrial targeting sequence (MTS) of PB1-F2 is an amphipathic α-helix at the carboxyl terminus, the interaction of PB1-F2 at its N-terminus with HAX-1 would not interfere with its trafficking and translocation to the mitochondria during viral infection." (PMID 29576744, 2018).
B-cell lymphomas (1 paper, 2022). "Recently, a research showed that the decomposition of HAX-1 induced CD in mankind B-cell lymphomas, confirming the critical effects of HAX-1 on regulating cellular survival." (PMID 35602302, 2022).
cerebellar ataxia (1 paper, 2021). A neurological syndrome characterized by clumsy and uncoordinated movement of the limbs, trunk, and cranial muscles. "Previous work has shown that a human Kv3.3 mutant channel (G592R Kv3.3), which is linked to late-onset spinocerebellar ataxia, binds the cell survival protein Hax-1." (PMID 33741962, 2021). "Here, the authors show that the known Kv3.3 channel complex with Hax1, which affects spinal cerebellar ataxia, regulates the enzyme Tank Binding Kinase 1, modulating survival of cerebellar neurons." (PMID 33741962, 2021).
cerebellar degeneration (1 paper, 2021). Degeneration of the cerebellum. "To probe further how an abnormal interaction between Kv3.3 and Hax-1 leads to cerebellar degeneration, we used CRISPR/Cas9 gene editing to generate homozygous G592R Kv3.3 knock-in mice." (PMID 33741962, 2021).
cerebral infarction (1 paper, 2024). An ischemic condition of the brain, producing a persistent focal neurological deficit in the area of distribution of the cerebral arteries. "TUNEL staining showed that compared with the negative control group, the density of TUNEL staining was significantly reduced in the cerebral infarction of the HAX-1 overexpression group; while the highest expression was observed in the HAX-1 knockdown group." (PMID 38811533, 2024). "In summary, our study showed HAX-1 attenuated microglial pyroptosis both in vivo and in vitro and reduced the inflammatory responses in cerebral infarction through inhibition of proinflammatory cytokines such as IL-1 and IL-18." (PMID 38811533, 2024). "The effects of HAX-1 expression on cerebral infarction following tMCAO were detected by TTC staining and H&E staining methods in three HAX-1 groups." (PMID 38811533, 2024). "At the same time, HAX-1 expression was found to be reduced in cerebral infarction." (PMID 38811533, 2024). "Although the levels of Caspase1 and Gasdermin D decreased after cerebral infarction in all three groups, the expression levels of Caspase1 and Gasdermin D were higher in the HAX-1 overexpression group than those in the control group, and the knockout group showed the lowest levels of expression." (PMID 38811533, 2024). "Our current study demonstrates that the expression levels of HAX-1 were reduced in the ischemic area in a mouse model of cerebral I/R, while the overexpression of HAX-1 protein could reduce the area of cerebral infarction and the degree of microglia pyroptosis." (PMID 38811533, 2024). "In conclusion, Our findings support that HAX-1 exhibits a protective role in cerebral I/R injury, and further study on HAX-1 expression regulation will contribute to cerebral infarction therapy." (PMID 38811533, 2024). "In conclusion, HAX-1 protein plays a protective role in cerebral ischemia-reperfusion injury by regulating pyroptosis in microglia and the release of inflammatory mediators, thus suggesting that HAX-1 protein presents a novel therapeutic target for cerebral infarction." (PMID 38811533, 2024). "Moreover, in the absence of HAX-1 protein in brain tissue, the severity of cerebral infarction increased, and the nervous cell apoptosis also increased significantly." (PMID 38811533, 2024).
Cerebral ischemia (1 paper, 2024). Restriction of arterial blood supply to the brain associated with insufficient oxygenation to support the metabolic requirements of the tissue. "Initially, we detected the expression of HAX-1 in the mouse model of tMCAO and found that the expression of HAX-1 decreased after cerebral ischemia." (PMID 38811533, 2024). "Similarly, the latest research shows that under an ischemic and hypoxic situation, NOX2 protein in neuronal cells induces the increase of ROS, reduces the expression of HAX-1, and leads to neuronal apoptosis after cerebral ischemia." (PMID 38811533, 2024).
gastric cancer (1 paper, 2015). A primary or metastatic malignant neoplasm involving the stomach. "The qRT-PCR experiments were designed to detect the expression levels of the top 5 ranking HAX1, RNF2, PIM3, TPP1 and CAV1 genes in addition to the seed proteins ABCB1, AKT1 and BCL2 in both the SGC7901 gastric cancer cell line and the Adriamycin resistant SGC7901/ADR cell line." (PMID 26039373, 2015).
glaucoma (1 paper, 2022). Increased pressure in the eyeball due to obstruction of the outflow of aqueous humor. "In addition, we also quantitatively analyzed both groups for the expression of apoptosis-related (BAD, BAX, BCL2L10, and XIAP) and autophagy-associated (HAX1 and Beclin-1) marker proteins, since both signaling cascades are supposed to be highly involved in the molecular pathogenesis of glaucoma." (PMID 36313990, 2022).